NOTCH2NLB (notch 2 N-terminal like B)
Description:
Human-specific protein that promotes neural progenitor proliferation and evolutionary expansion of the brain neocortex by regulating the Notch signaling pathway. Able to promote neural progenitor self-renewal, possibly by down-regulating neuronal differentiation genes, thereby delaying the differentiation of neuronal progenitors and leading to an overall final increase in neuronal production. Acts by enhancing the Notch signaling pathway via two different mechanisms that probably work in parallel to reach the same effect. Enhances Notch signaling pathway in a non-cell-autonomous manner via direct interaction with NOTCH2. Also promotes Notch signaling pathway in a cell-autonomous manner through inhibition of cis DLL1-NOTCH2 interactions, which promotes neuronal differentiation.
Tractability: Antibody: UniProt places it where antibodies can reach, with high confidence; its Gene Ontology location is reachable by antibodies, with high confidence; UniProt predicts a signal peptide or a membrane-spanning region.
Gene: Protein-coding gene on chromosome 1 (148,597,331 to 148,679,746, reverse strand). Ensembl gene ENSG00000286019.
Subcellular location: Secreted
Pathways (Reactome):
Signal Transduction: Expression of NOTCH2NL genes; NOTCH2 Activation and Transmission of Signal to the Nucleus
Gene Ontology:
Molecular function: Notch binding; protein binding; calcium ion binding
Biological process: cerebral cortex development; positive regulation of Notch signaling pathway
Cellular component: extracellular region
Genetic constraint (gnomAD): Loss-of-function variants: 0 observed, 2.13 expected, observed/expected ratio (o/e) 0, 90% interval 0 to 1.3. That is too few expected variants to judge how well the gene tolerates losing a copy. Missense variants: 5 observed, 27.34 expected, observed/expected ratio (o/e) 0.18, 90% interval 0.095 to 0.38. Synonymous variants: 2 observed, 12.83 expected, observed/expected ratio (o/e) 0.16, 90% interval 0.063 to 0.49.
Homologues: Orthologues: Drosophila melanogaster N (42% identical), Caenorhabditis elegans lin-12 (8% identical), zebrafish notchl (1% identical). Paralogues in human: NOTCH2NLC (99% identical), NOTCH2NLA (94% identical), NOTCH2 (93% identical), NOTCH2NLR (90% identical), NOTCH1 (45% identical), NOTCH3 (38% identical), SNED1 (12% identical).
Diseases named in the same sentence as NOTCH2NLB in open-access papers:
NOTCH2NLB is named in the same sentence as 4 diseases in open-access papers, as found by Europe PMC text mining. Sharing a sentence is not in itself a finding about the gene and the disease. The quoted sentences say what the papers report.
microcephaly (2 papers, 2021 to 2025). A congenital or acquired developmental disorder in which the circumference of the head is smaller than normal for the person's age and sex. "NBPF14 (Neuroblastoma Breakpoint Family Member 14) is an interesting candidate for a role in microcephaly, not only as it co-evolved with NOTCH2NLB and is located in the chromosomal region that is associated with 1q21.1 distal syndrome, but also as it belongs to the NBPF gene family." (PMID 34063381, 2021). "Specifically, combining these organoids with rescue experiments involving NOTCH2NLB and NBPF14, either individually or together, using electroporation could be a fruitful approach to understand the role of these genes in the microcephaly associated with this syndrome." (PMID 40138416, 2025). "NOTCH2NLB and NBPF14 map to the 1q21.1 genomic region, which is associated with the 1q21.1 distal duplication/deletion syndrome, a neurodevelopmental disorder linked to various neurological symptoms including autism spectrum disorders, schizophrenia, microcephaly, and macrocephaly." (PMID 40138416, 2025). "The present functional data on NBPF14 and its genomic localization (close to NOTCH2NLB) between the two breakpoints of the 1q21.1 distal duplication/deletion syndrome suggest NBPF14 as a novel and likely important player in the macrocephaly/microcephaly associated with this syndrome." (PMID 40138416, 2025). "Moreover, as two other human-specific genes are directly adjacent to NOTCH2NLA and NOTCH2NLB—that is, NBPF10 and NBPF14, respectively—mutations affecting these genes could be potentially important contributors to microcephaly." (PMID 34063381, 2021).
NOTCH2NLB also shares sentences with these, for which no sentence is quoted: autism spectrum disorder (1 paper); neurodevelopmental disorder (1); schizophrenia (1).